CXCR4 (C-X-C motif chemokine receptor 4)
Diseases named in the same sentence as CXCR4 in open-access papers (continued):
Sharing a sentence is not in itself a finding about the gene and the disease.
COVID-19 (continued). "As regards the chemokine receptors, CXCR2 and CXCR4, we found significantly reduced levels of CXCR4 in severe COVID-19 patients and only a non-significant trend of reduction for CXCR2." (PMID 37568438, 2023). "However, in the severe and convalescence from moderate conditions, the most active multi-receptor unit is the heteromeric complex containing CD74 and CXCR4, indicating differences in the types of MIF-specific interactions across COVID-19 conditions." (PMID 36105110, 2022). "Other recent studies have also observed increased levels of CXCR4 with levels higher in severe than in non-severe COVID-19 patients." (PMID 34975885, 2021). "Therefore, this network also displays the contribution of increased pro-inflammatory molecules or signaling pathways (IL1B, IL6, IL8, IL17a) and upregulated chemokine signaling (CXCR4 signaling, CCL5) observed in severe COVID-19 outcomes." (PMID 33941085, 2021). "Many of these cells were bystander (non-SARS-CoV-2-specific) CXCR4+ CD69+ T cells whose numbers in blood increased prior to death from COVID-19." (PMID 34636722, 2021). "Distinct immunotypes were evident in COVID-19 patients, with altered expression of several receptors involved in activation, adhesion, and migration of granulocytes (e.g., CD62L, CD11a/b, CD69, CD63, CXCR4)." (PMID 34548411, 2021). "We also observed significant up-regulation of CD66b, CD177, CD11b, CXCR4, CD147 (the receptor that binds the spike protein of SARS-CoV-2), and CD63 in mature neutrophils from COVID-19 patients compared to healthy controls, as well as significant down-regulation of CXCR2." (PMID 34548411, 2021). "In addition, MSCs alter B cell trafficking phenotype, including downregulation of CXCR4 and CXCR5, that are differentially regulated in COVID-19 (see section “B Cell Trafficking Phenotype section”)." (PMID 34595175, 2021). "It is used to downregulate the expression of CXCR4, which leads to the inhibition of the uncontrolled production of a variety of key inflammatory cytokines by monocytes that play a central role in the cytokine storm prompted by SARS-CoV-2 in patients with severe COVID-19." (PMID 39407172, 2024). "It is also interesting to note that in the transcriptomic studies, the significantly reduced expression of the MIF co-receptor CXCR4 paralleled that of CD74, suggesting that a common mechanism of downregulated expression could occur during moderate and severe cases of COVID-19." (PMID 37568438, 2023). "Significantly increased percentages of CXCR4-expressing CD74+ CD4+ T cells (mean: healthy 61.5%, mild 84.0%, severe 81.0%) and CXCR4 CD74+ CD8+ T cells (mean: healthy 54.2%, mild 78.4%, severe 71.7%) were observed in both groups of COVID-19 patients in comparison to healthy controls." (PMID 37946732, 2023). "On the other hand, SDF-1α receptor CXCR4, involved in neutrophil trafficking from the bone marrow and local retention, was significantly higher, pointing to decreased signaling engagement, whereas the maturation marker CD15 was significantly lower in acute COVID-19 cells." (PMID 35007290, 2022). "In patients with severe COVID-19, CXCR4 might play a crucial role in recruitment of NK cells and T cells as indicated by our and previous analysis of the BAL fluid dataset, but further studies are needed to unravel CXCR4-mediated lung-infiltration." (PMID 35371005, 2022). "Last, expression of CXCR2 and CXCR4, which define neutrophil maturation stages and regulate their trafficking from bone marrow, was detected in the two neutrophil clusters identified in patients with COVID-19 (aged and nonaged neutrophils)." (PMID 33622974, 2021).
renal cell carcinoma (53 papers, 2005 to 2025). "In renal cell carcinoma, a meta-analysis of 1203 patients from 14 eligible studies confirmed that CXCR4 expression is associated with increased risk, progression, and prognosis, and with poor survival." (PMID 32260318, 2020). "The notion that strong CXCR4 expression is indicative of an undifferentiated state is consistent with a significant association of CXCR4 with advanced dedifferentiated renal cell carcinoma." (PMID 22880115, 2012). "Strong CXCR4 expression of renal cell carcinoma was significantly associated with advanced T-status (P = .039), tumor dedifferentiation (P = .0005), and low hemoglobin (P = .039)." (PMID 19266088, 2008). "In summary, strong CXCR4 expression was significantly associated with advanced dedifferentiated renal cell carcinoma." (PMID 19266088, 2008). "Previous studies have indicated that the nuclear localization of CXCR4 is more prevalent in renal cell carcinoma (RCC) tissues, especially during metastases, and is associated with poor prognosis." (PMID 39195225, 2024). "CXCR4, a commonly reported receptor for CXCL14, has been implicated in the regulation of tumor metastasis in renal cell carcinoma and endometrial cancer." (PMID 40898244, 2025). "documented that the pharmacological inhibition of NMMHC-IIA using blebbistatin effectively suppressed the nuclear translocation of CXCR4, thereby attenuating the metastatic potential of renal cell carcinoma (RCC) cells." (PMID 39440063, 2024). "The objective of the current study was a comprehensive analysis of CXCR4 expression in primary renal cell carcinoma, metastatic tissue, and other histological subtypes of renal neoplasms including benign lesions." (PMID 36982302, 2023). "Other studies have shown that MYH9 binds to CXCR4 and promotes the migration and invasion of renal cell carcinoma." (PMID 36374212, 2022). "There is also evidence for HIF-dependent activation of CXCR4 under hypoxic conditions in renal cell carcinoma." (PMID 33467498, 2021). "CXCR4 showed different subcellular distribution in pathological specimens of renal cell carcinoma derived from different sources." (PMID 34022911, 2021). "CXCR4 is a G-protein-coupled chemokine receptor that is upregulated in many cancers, including thyroid, breast, pancreatic, prostate, and kidney cancers, renal cell carcinoma, and OC." (PMID 32983229, 2020). "Elaborate experiments by Gassenmaier and colleagues demonstrated that CXCR4 was upregulated in CSCs and that the inhibition of CXCR4 in renal cell carcinoma through the use of AMD3100 would hamper CSCs ability to proliferate and formation of tumorspheres." (PMID 32823711, 2020). "Previous studies showed that upregulation of CXCR4 was strongly correlated with poor prognosis in renal cell carcinoma." (PMID 32983229, 2020). "Some studies have described CXCR4 nuclear localization in metastatic lesions of renal cell carcinoma (RCC), which has been suggested to be correlated with cancer metastasis." (PMID 30177838, 2019). "Previously, recombinant CXCR4-RNAi plasmids were found to reduce CXCR4, inhibit cell growth, invasiveness, and migration, and induce cell apoptosis in renal cell carcinoma in vitro." (PMID 24647809, 2014). "CXCR4 was found to be transactivated by hypoxia-induced factor-1α (HIF-1α) at the transcriptional level in renal cell carcinoma." (PMID 23082154, 2012). "High levels of CXCR4, CXCR7 and SDF-1 were associated with poor overall survival and recurrence-free survival in renal cell carcinoma patients." (PMID 23039915, 2012). "We analyzedthe expression profile of CXCR4 in aseries of human renal cell carcinoma cell lines and 113 patients' samples forwhich exact tumor staging and followup data were available and correlated theexpression profile with clinicopathological data." (PMID 19266088, 2008). "The aim of this study was to evaluate the influence of CXCR4 expression on the progression of human renal cell carcinoma." (PMID 19266088, 2008).
renal cell carcinoma (continued). "Strong CXCR4 expression significantly correlated withdedifferentiated (P = .0005) and progressed renal cell carcinoma, indicated by T-status (P = .039)." (PMID 19266088, 2008). "The oncogenic function of CXCR4 exhibits tissue-specific regulation: while DUXAP8 lncRNA upregulates CXCR4 via miR-223 sequestration in papillary thyroid carcinoma, miR-1246-mediated CXCR4 suppression attenuates proliferative and migratory capacities in renal cell carcinoma." (PMID 40396123, 2025). "CXCR4 is an important marker of renal cell carcinoma stem cells." (PMID 35342431, 2022). "Additionally, miRNA-1246 attenuates renal cell carcinoma’s proliferative and migratory abilities by downregulating CXCR4." (PMID 36551682, 2022). "Accordingly, CXCR7 together with CXCR4 predicts worse prognosis in renal cell carcinoma patients." (PMID 33937018, 2021). "Our findings are consistent with the previous reports that CXCR4 functions in maintenance of renal cell carcinoma-initiating cells derived from renal carcinoma cell line RCC-26 an RCC-53 and its expression in mesenchymal stem cells is regulated by Notch signaling." (PMID 28279221, 2017). "In human renal cell carcinomas in particular twopotassium ion channels of the ether-a-go-go (EAG) family were reported to beup-regulated.An additional possible target is CXCR4, a C-X-C chemokine receptor that has beenreported by multiple groups to be up-regulated in renal cancers." (PMID 23144724, 2012). "Human renal cell carcinoma revealed variable intensities of CXCR4 expression." (PMID 19266088, 2008). "CXCR4 expression of renal cell carcinoma was assessed by immunohistochemistry in 113 patients." (PMID 19266088, 2008). "C-X-C Motif Chemokine Receptor 4 (CXCR4) is part of the human chemokine system and is involved in the progression and metastasis development of renal cell carcinoma (RCC)." (PMID 37513907, 2023). "However, the role of CXCR4 protein expression in RCC remains controversial, and its nuclear or cytoplasmic location appears to be heterogenous between primary and metastases in renal cell cancer as well as in variant renal histologies and benign lesions." (PMID 37513907, 2023). "Therefore, nuclear translocation of CXCR4 may be one of the important mechanisms leading to invasion and metastasis of malignant tumors such as renal cell carcinoma." (PMID 34022911, 2021). "In Renal Cell Carcinoma (RCC), the effect of the new CXCR4 antagonist, R54, was explored in peripheral blood (PB)-Tregs isolated from primary RCC patients." (PMID 38704478, 2024). "C-X-C Motif Chemokine Receptor 4 (CXCR4) is part of the human chemokine system and involved in progression and metastasis in renal cell carcinoma (RCC)." (PMID 36982302, 2023). "The expression of CXCR4, CXCR7 and SDF-1 in specimens from 97 renal cell carcinoma patients was evaluated by immunohistochemistry on a tissue microarray." (PMID 23039915, 2012). "The aim of this study was to evaluate the prognostic impact of the expression of the chemokine SDF-1 and its receptors CXCR4 and CXCR7 in patients with renal cell carcinoma." (PMID 23039915, 2012). "In contrast, studies in VHL-related renal cell carcinoma and retinal hemangioblastoma high levels of CXCR4 and VEGF, and not CXCL12, were found." (PMID 26920352, 2016). "Two Phase II studies, one in renal cell carcinoma [NCT01391130] and one in small cell lung cancer [NCT 01439568] have evaluated the efficacy of the CXCR4 peptidic inhibitor LY2410924® (Eli Lilly and Company) in combination with sunitinib and carboplatin/etoposide respectively." (PMID 24058588, 2013). "CXCR4, CXCR7 and SDF-1 may serve as useful prognostic markers and therapeutic targets for renal cell carcinoma." (PMID 23039915, 2012). "Furthermore, CXCR4 is a cancer stem cell marker in PDAC, prostate cancer, and renal cell carcinoma." (PMID 32260318, 2020).
cervical carcinoma (48 papers, 2009 to 2025). A carcinoma arising from either the exocervical squamous epithelium or the endocervical glandular epithelium. "In HPV-associated cancers such as cervical cancer, GPCRs can be activated by the interaction of chemokines CXCR4 and ACKR3 with glycosaminoglycans of the extracellular matrix (ECM), acting as targets of oncogenic pathways at the cellular level of cancer cells and TME." (PMID 35879796, 2022). "C-X-C chemokine receptor type 4 (CXCR4) was also found to be highly expressed in HPV-positive cervical cancer cells." (PMID 40655948, 2025). "The p65 subunit of NF-κB is O-GlcNAcylated at Ser-550 and 551 upon NF-κB activation in PDAC, and promotes lung metastasis by activating C-X-C chemokine receptor type 4 (CXCR4) expressions in cervical cancer cells." (PMID 39178944, 2024). "Treatment targeting the CXCL12/CXCR4 pathway increased the efficacy of radiotherapy of locally advanced cervical cancer." (PMID 36419891, 2022). "Apart from tumor growth, O-GlcNAcylation of NF-κB subunit p65 also promotes lung metastasis of cervical cancer cells via upregulating CXCR4 expression." (PMID 35432358, 2022). "Point mutated p65 at Thr322 or Thr352 in HeLa cells decreased CXCR4 expression compared to transfection with wild-type p65, indicating site specific p65 O-GlcNAcylation contributes to the regulation of CXCR4 expression in cervical cancer cells." (PMID 35432358, 2022). "From the Kaplan–Meier overall survival analysis, the level of only CXCR4 expression was significantly related to the overall survival of patients with cervical cancer, while the rest of the hub genes’ survivability was lower in the high expression group." (PMID 33946372, 2021). "Another study in cervical cancer also found that NF-κB promotes cancer cell migration to the lung via upregulation of CXCR-4 expression." (PMID 33854604, 2021). "The CXCL12/CXCR4 signaling pathway plays an important role in the development of cervical cancer, the further course of this malignant disease, the development of metastases, and the response to radiation therapy." (PMID 34833360, 2021). "In contrast to former studies, a more recent study shows that the chemokine CXCL12 and its receptor CXCR4 are constitutively overexpressed in human cancers, especially cervical cancer." (PMID 34833360, 2021). "In this sense, CXCR4+ cells lines (the cervix cancer HeLa and the human colorectal SW1417) were exposed to these materials at different times." (PMID 34208189, 2021). "And studies showed that CXCL12/CXCR4 pathways was associated with HPV infection as a co-factor, which means a high risk to the incidence of cervical cancer." (PMID 33344075, 2020). "In an animal model of cervical cancer, CXCR4 inhibition by plerixafor lead to better sensitivity to radiotherapy and reduced metastasis formation." (PMID 31810195, 2019). "The CXCL12/CXCR4 chemokine pathway is involved in cervical cancer pathogenesis and radiation treatment (RT) response." (PMID 31239542, 2019). "The results provide a strong rationale for future clinical trials of RTCT and plerixafor or another CXCL12/CXCR4 inhibitor aimed at improving the efficacy of frontline curative therapy for patients with cervical cancer and possibly other malignancies." (PMID 31239542, 2019). "We have previously found that CXCR4 expression influenced invasive properties of cervical carcinoma cells both in vitro and in vivo." (PMID 25888626, 2015). "In our study, we evaluated the level of CXCR4 expression in human samples (n = 31) obtained from cervical carcinoma patients." (PMID 25888626, 2015). "In women with genital tract pathologies, and cervical cancers in particular, expression of chemokine receptors such as CXCR4 and CCR5 is elevated." (PMID 25180120, 2014). "In this study, we investigated the role of the SDF-1/CXCR4 axis during cervical carcinoma growth and progression in vitro and in vivo." (PMID 24728301, 2014).
cervical carcinoma (continued). "We also found CXCR4 promoter hypermethylation in cervical cancer cell lines and primary biopsy samples." (PMID 25114911, 2014). "Cervical cancer cell line C-33A having increased expression of CXCR4 after TSA treatment showed increased cell adhesion by paracrine source of SDF-1α in comparison to untreated C-33A." (PMID 25114911, 2014). "In our study CXCR4 influenced invasive properties of cervical carcinoma cells both in vitro and in vivo." (PMID 24728301, 2014). "Most of the early studies on the role of CXCR4 in cervical cancer were performed using the HeLa cell line (cervical adenocarcinoma-derived cell), the first immortalized cell line developed for research purposes." (PMID 20049170, 2010). "Contribution of the SDF-1α/CXCR4 axis to the migration of cervix carcinoma cells was suspected; indeed a pro-migratory action of the SDF-1α has been reported in HeLa cells." (PMID 19325708, 2009). "SDF-1α protein is indeed highly synthesized at common metastatic sites, including bone marrow, liver and lung and CXCR4 is highly expressed on cervix cancer cells." (PMID 19325708, 2009). "Although currently there is not enough evidence demonstrating the role of [68Ga]Ga-Pentixafor in cervical cancer, CXCR4-PET imaging could potentially be used for prognostication and patient selection for CXCR4-targeting therapies." (PMID 39997565, 2025). "The CXCL12/CXCR4 chemokine pathway is expressed in cervical cancer." (PMID 34833360, 2021). "In conclusion, this study demonstrates that RTCT increases CXCL12/CXCR4 signalling in cervical cancer, leading to intratumoral accumulation of MDSCs and other myeloid cell populations that may contribute to disease recurrence." (PMID 31239542, 2019). "We have seen prolonged tumour growth delay in several PDX tumour models with this treatment regimen, including those with either low or high baseline CXCR4 expression, suggesting that it may be broadly applicable in patients with cervical cancer." (PMID 31239542, 2019). "CXCR4 has been shown to be upregulated in many of the solid tumors including cervical cancer (CC)." (PMID 25114911, 2014). "Chemokine receptors like CXCR4 are known to play a role in lymph node metastasis during advanced-stage disease; however their elevated expression in cervical cancers could potentially be hijacked by HIV for entry." (PMID 25180120, 2014). "Thus, our data suggest CXCR4 as a novel target for prevention of cervical carcinoma growth and metastasis." (PMID 24728301, 2014). "Interestingly, we found downregulation of CXCR4 at both transcript and protein level in cervical cancer cell lines and primary tumors." (PMID 25114911, 2014). "In addition, transcriptional activation of the CXCR4 promoter is described in cervix carcinoma and immunohistochemistry has shown high CXCR4 expression on cervix cancer cells." (PMID 19325708, 2009). "Finally, from the overall analysis and discussion we proposed that CXCR4 could be a novel target for the prevention of cervical carcinoma growth and metastasis." (PMID 33946372, 2021). "The feasibility of imaging CXCR4 expression using [68Ga]Ga-Pentixafor PET/CT in cervical cancer has been investigated and correlated with immunohistochemistry stains of cervical cancer tissue samples." (PMID 39997565, 2025). "In cervical cancer, ITGA5 influences tumor cell responses to CXCL12 by regulating CXCR4 expression, thereby promoting cell migration and invasion." (PMID 40517358, 2025). "A genetic analysis of cervical cancer tumor tissue was conducted to assess the expression of STAT3, Snail, PD‐1, HPV16, HPV18, FOXP3, EXPORTIN 5 (XPO5), CXCR4, CXCL12, and CD8." (PMID 41263059, 2025). "In the case of cervical cancer and human endothelial cells, hsa-miR-9-5p has been observed to promote angiogenesis by targeting SOCS5 and CXCR4, respectively." (PMID 38628314, 2024).